TUG1 (taurine up-regulated 1)
Diseases named in the same sentence as TUG1 in open-access papers (continued):
Sharing a sentence is not in itself a finding about the gene and the disease.
bladder cancer (continued). "lncRNA TUG1 regulated CCND2, through EZH2-related miR-194-5p silencing, to promote the growth of bladder cancer cells and confer cisplatin resistance." (PMID 34039257, 2021). "To date, many aberrantly expressed lncRNAs have been identified in bladder cancer, including upregulated lncRNAs, H19, MALAT1, SNHG16, TUG1, UCA1, TINCR and Linc-UBC1; and downregulated lncRNAs, BANCR and MEG3." (PMID 29719633, 2018). "A previous study found that TUG1 promoted cancer cell invasion and radioresistance through inducing epithelial-to-mesenchymal transition (EMT) in bladder cancer." (PMID 28376901, 2017). "Quantitative real-time PCR (qRT-PCR) was conducted to measure the expression of TUG1 and HMGB1 mRNA in bladder cancer tissues and cell lines." (PMID 28376901, 2017). "Taken together, all these results revealed that radiation treatment promotes the TUG1 and HMGB1 expression in bladder cancer cell lines." (PMID 28376901, 2017). "The expression level of TUG1 and HMGB1 mRNA and protein was about twice higher in bladder cancer tissues than that in adjacent normal tissues." (PMID 28376901, 2017). "Like UCA1, another lncRNA Taurine upregulated gene 1 (TUG1), also promotes EMT and invasion in bladder cancer through acting as a ceRNA for miR-145 and liberation of expression of the miR-145 target ZEB2." (PMID 28430163, 2017). "TUG1-miR-145-ZEB2 constitutes a ceRNA regulatory network, and regulates epithelial to mesenchymal transition and radioresistance in human bladder cancer cells." (PMID 27362796, 2016). "In bladder cancer, miR-145 was found to also regulate ZEB2, but, interestingly, the long non-coding RNA taurine up-regulated 1 (TUG1) was found to modulate the levels of miR-145 by acting as a competing endogenous RNA (ceRNA) for miR-145." (PMID 26784241, 2016). "lncRNA TUG1 expression by miR142-mediated zinc finger E-box binding homeobox 2 (ZEB2), through inactivating the Wnt/β-catenin pathway, promoted the proliferation of bladder cancer cells and induced apoptosis." (PMID 34039257, 2021). "Similarly, other overexpressed lncRNAs namely TUG1 and MALAT1 were also found to act as ceRNA in bladder cancer and cervical cancer." (PMID 29719612, 2018). "TUG1 was significantly increased in bladder cancer cell lines (SW780, HT1376, BIU87 and T24) compared with normal bladder epithelial cell line HCV-29, especially in SW780 and BIU87 cells." (PMID 28376901, 2017). "The levels of TUG1 and HMGB1 were remarkably increased in bladder cancer tissues and cell lines." (PMID 28376901, 2017). "Another study detected TUG1 transcripts in 54 bladder cancer tissues by RT-qPCR; expression in normal tissues was not investigated." (PMID 28430799, 2017). "In bladder cancer, it has been proved that the silencing of lncRNA Taurine-upregulated gene 1 (TUG1) improves radiation sensitivity by inhibiting HMGB1 expression, resulting in less cell proliferation, more cell apoptosis and decreased colony survival in bladder cancer cell lines under radiation." (PMID 32122355, 2020). "Considering the positive correlation between TUG1 and HMGB2 expression in bladder cancer tissues and cells, as well as their consistent change under radiation treatment, we assumed that TUG1 may affect the radiosensitivity of bladder cancer cells via regulating the expression of HMGB2." (PMID 28376901, 2017). "The expression of TUG1 and HMGB1 mRNA was measured by qRT-PCR and the HMGB1 protein level was determined by western blot in bladder cancer tissues and adjacent non-cancer tissues, respectively." (PMID 28376901, 2017).
hepatocellular carcinoma (48 papers, 2015 to 2025). A malignant tumor that arises from hepatocytes. "One such member of the nuclear transcription factor family, SP1 was recently identified to cause an elevation in TUG1 in hepatocellular carcinoma." (PMID 35508523, 2022). "lncRNA TUG1 was used as a non-invasive, cost-effective, and complementary biomarker in viral hepatitis C and viral hepatitis C-associated hepatocellular carcinoma." (PMID 34039257, 2021). "Conversely, the expression of lncRNA TUG1 in viral hepatitis C and viral hepatitis C-associated hepatocellular carcinoma decreased." (PMID 34039257, 2021). "In esophageal, gastric, colorectal, and hepatocellular cancer as well as cholangiocarcinomas, lncRNA taurine-upregulated gene 1 (TUG1) is involved in causing resistance to chemotherapy." (PMID 29967761, 2018). "Recently, increasing evidence had suggested that aberrant TUG1 expression was associated with non-small cell lung cancer, hepatocellular carcinoma, and ESCC." (PMID 30519392, 2018). "However, the mechanism underlying the effect of TUG1 and the Hedgehog pathway in hepatoma remains undefined." (PMID 29029483, 2017). "A study using SCARLET to profile m6A in lncRNAs tested 10 sites in TUG1 for the presence of m6A in HeLa, human embryonic kidney–293T, and hepatocellular carcinoma (HEPG2) cell lines." (PMID 40779635, 2025). "This study highlights the pivotal role of lncRNAs in cancer metabolism and positions TUG1 as a potential therapeutic target in hepatocellular carcinoma." (PMID 41024611, 2025). "TUG1 is closely related to invasion, metastasis, proliferation and apoptosis in a variety of tumors, but its specific mechanism of action in hepatocellular carcinoma requires further exploration." (PMID 37813900, 2023). "The overexpression of TUG1 promoted cell metastasis and glycolysis via the TUG1/miR-455-3p axis in hepatocellular carcinoma." (PMID 36639695, 2023). "In hepatocellular carcinoma, TUG1 was found to play important roles in immune-related pathways, such as antigen processing and presentation, and chemokine receptors." (PMID 37813900, 2023). "Secondly, more comprehensive in vivo and in vitro studies are necessary to elucidate the mechanisms of TUG1 promotes hepatocellular carcinoma immune evasion via upregulating the JAK2/STAT3/PD-L1 signaling pathway." (PMID 37813900, 2023). "miR-216b-5p poor expression has once been confirmed in hepatocellular carcinoma; TUG1/miR-216b-5p conforms to the mode of miR-sponge, and TUG1-mediated spongy effect on miR-216b-5p aggrandizes tumors to progress." (PMID 35475502, 2022). "For example, lncRNA TUG1 is considerably expressed in hepatoma cells and augments the invasion and migration of hepatocellular carcinoma through targeting the miR-137/AKT2 axis." (PMID 35874626, 2022). "lncRNA TUG1 promoted hepatoma cell proliferation, migration and invasion, inhibited apoptosis, and up-regulated AURKA expression in hepatocellular carcinoma." (PMID 34039257, 2021). "For example, SP1 overexpresses the long noncoding RNA TUG1, and promotes tumor growth in hepatocellular carcinoma." (PMID 34185412, 2021). "Our group demonstrated that taurine upregulated gene 1 (TUG1) is highly expressed in hepatocellular carcinoma (HCC) specimens compared to adjacent normal tissues." (PMID 32331347, 2020). "A previous report has indicated SP1 as an upstream mediator of TUG1 expression in hepatocellular carcinoma, but the significance of this interaction in regard to CRC is unknown." (PMID 35508523, 2022). "Although the effects of TUG1 on apoptosis were similar to those reported previously, earlier experiments by our group showed that TR-overexpressing hepatoma cells treated with T3 were apoptosis-resistant, suggesting that the effect of T3/TR on apoptosis is not mediated by TUG1." (PMID 31973032, 2020). "Up regulation of TUG1 can promote cell growth and apoptosis in hepatocellular carcinoma." (PMID 27580177, 2016).
hepatocellular carcinoma (continued). "Long non-coding RNA TUG1 is highly expressed in hepatocellular carcinoma (HCC), driven by METTL3-mediated m6A modification." (PMID 41346602, 2025). "The long non‐coding RNA taurine‐upregulated gene 1 (TUG1) is upregulated in hepatocellular carcinoma (HCC)." (PMID 38981064, 2024). "MALAT1 and Taurine upregulated gene 1 (TUG1), which are upregulated in various tumours including HCC, colorectal cancer (CRC), breast cancer, glioblastoma, and hepatocellular carcinoma promote angiogenesis by increasing VEGF expression through sponging miRNAs." (PMID 35052495, 2022). "However, the exact function of TUG1 in hepatoma and its effect on the binding of miR-132 to its target gene Shh remain unclear." (PMID 29029483, 2017). "miR-455-3p, controlled by taurine upregulated gene 1 (TUG1), represses AMPKb2 expression and contributes to increased levels of Snail and HK2, thus leading to enhanced motility and invasion and glycolysis of hepatoma cells." (PMID 35348905, 2022). "The present study investigated the role of TUG1 and its downstream genes miR-29a and IFITM3 in the occurrence and development of hepatocellular carcinoma (HCC)." (PMID 34659578, 2021). "In conclusion, T3/TR regulates expression of TUG1 and AFP in a hepatoma cell line, which are significantly positively correlated." (PMID 31973032, 2020). "Several recent studies indicated that TUG1 regulate genes expression by binding with EZH2 to affect cell proliferation in human non-small cell lung cancer, gastric cancer and hepatocellular carcinoma." (PMID 28069000, 2017). "Increasing evidence suggests that taurine upregulated gene 1 (TUG1) is crucial for tumor progression; however, its role in hepatocellular carcinoma (HCC) and the underlying mechanisms are not well characterized." (PMID 35193488, 2022). "The level of alpha-fetoprotein (AFP) in patients with non-hepatitis B/non-C hepatocellular carcinoma (NBNC-HCC) was positively correlated with that of lncRNA TUG1, and the prognosis was poor." (PMID 34039257, 2021). "However, the overall biological role and clinical significance of TUG1 in hepatocellular carcinoma (HCC) remain largely unknown." (PMID 31920462, 2020). "For example, microRNA-3653 targeting ITGB1 restrains the growth and metastasis in hepatocellular carcinoma; microRNA-183-5p inhibits cervical cancer aggressiveness through targeting ITGB1; lncRNA TUG1/miR-29c axis influences cell proliferation, invasion, and migration in PC by regulating ITGB1." (PMID 31693728, 2019). "Moreover, TUG1 has been proved to regulate genes expression by binding with EZH2 in human non-small cell lung cancer, gastric cancer and hepatocellular carcinoma." (PMID 30519392, 2018). "TUG1 upregulation was also observed in all examined hepatocellular carcinoma and hepatoblastoma cells compared with the nonmalignant QSG-7701 and L01 hepatocytes." (PMID 27362796, 2016).
colorectal cancer (42 papers, 2016 to 2024). A primary or metastatic malignant neoplasm that affects the colon or rectum. "Additional evidence shows that transient knockdown of TUG1 causes increased sensitivity to methotrexate in colorectal cancer cells." (PMID 35582574, 2019). "This hints that the IGF2BP2/TUG1 axis is an underlying target for colorectal cancer treatment." (PMID 35014946, 2022). "Moreover, the survival and staging of prostate and colorectal cancer have been found to be associated with lncRNA TUG1, demonstrating its potential for cancer prognosis." (PMID 34766130, 2020). "Here, we observed lncRNA TUG1 was associated to the 5-Fu resistance in colorectal cancer." (PMID 31528224, 2019). "TUG1 is emerging as a potential biomarker in colorectal cancer (CRC) for early detection, prognosis prediction, and evaluating therapeutic responses." (PMID 39339648, 2024). "In vitro studies have indicated the involvement of TUG1 in the development of various types of cancers, such as breast cancer, ovarian cancer, and colorectal cancer." (PMID 39339648, 2024). "SP1 upregulated lncRNA TUG1 and promoted the tumorigenesis of colorectal cancer cells by TUG1/miR-421/lysine demethylase 2A (KDM2A)/ERK axis." (PMID 37686205, 2023). "TGF-β/Twist11/EMT regulates colorectal cancer cell migration and invasion mediated by long non-coding RNA TUG1." (PMID 36639679, 2023). "lncRNA TUG1 mediated 5-fluorouracil resistance by acting as a competing endogenous RNA of miR-197-3p in colorectal cancer." (PMID 36595551, 2023). "The long non-coding RNA (lncRNA) taurine up-regulated gene 1 (TUG1) acts as tumor-promoting factor in colorectal cancer (CRC)." (PMID 35508523, 2022). "To summarize, our study has figured out the oncogenic function of IGF2BP2-stabilized TUG1 in colorectal cancer." (PMID 35014946, 2022). "Nonetheless, more studies are still in need to further investigate other molecular mechanisms of TUG1 affecting colorectal cancer." (PMID 35014946, 2022). "LncRNA TUG1 underlined a tumor promotive property via impairing miR-421-mediated suppression of KDM2A and activating the ERK signaling in colorectal cancer cells." (PMID 35928868, 2022). "lncRNA TUG1 promoted the proliferation and migration of colorectal cancer cells through the miR-145-5p/TRPC6 pathway, EMT pathway, miR-26a-5p/MMP14/p38MAPK/Hsp27 axis, Twist1/EMT signal pathway, or by overexpression." (PMID 34039257, 2021). "Regulation of the TWIST transcription factor was previously shown through mechanistic experiments to be the mechanism through which lncRNA TUG1 controlled malignant cell propagation and motility in colorectal cancer." (PMID 34766130, 2020). "TUG1 knockdown re-sensitized the 5-Fu resistance in colorectal cancer cells, which were 5-Fu-resistant colorectal cell line." (PMID 31528224, 2019). "TUG1 mediates MTX resistance in colorectal cancer via sponging miR-186 that targets CPEB2 increasing its protein levels that play an important role in tumorigenesis and chemoresistance." (PMID 31632922, 2019). "Recent literatures reported that TUG1 was high-expressed in several malignant tumors, including gastric cancer, colorectal cancer and pancreatic cancer, which indicated TUG1 acted as an oncogene in these tumors." (PMID 29179467, 2017). "Similarly, TUG1 was found to be highly expressed in colorectal cancer and facilitated the progression of cancer." (PMID 36157241, 2022). "To investigate whether TUG1 affects colorectal cancer cells’ proliferation and resistance to cisplatin in vitro, we utilized the vector and TUG1 to transfect CRC cells (LoVo and HCT15), respectively." (PMID 35014946, 2022). "Moreover, TUG1 acts as a tumor-promoting lncRNA in multiple tumors, such as colorectal cancer, breast cancer, ovarian cancer, and cervical cancer." (PMID 34749662, 2021). "The emerging evidence suggested that TUG1 could affect the drug resistance by functioning as a ceRNA of miR-186 in colorectal cancer." (PMID 32390763, 2020).
colorectal cancer (continued). "However, two recent studies mentioned exosomal TUG1, in MCF-7 cells, the levels of TUG1 were moderately elevated in exosomes when compared to cells, and TUG1 was up-regulated in the serum exosomes of colorectal cancer (CRC) patients." (PMID 32438606, 2020). "The lncRNA TUG1 is required for TGF-β/TWIST1/EMT-mediated metastasis in colorectal cancer cells." (PMID 32669962, 2020). "Moreover, TUG1 was reported to be an oncogene in various types of human cancers, such as colorectal cancer, ovarian cancer, and gastric cancer." (PMID 30873207, 2019). "Taurine up-regulated gene 1 (TUG1) is a cancer progression related lncRNA in some tumor oncogenesis; however, its role in colorectal cancer (CRC) remains unclear." (PMID 26856330, 2016). "TUG1 may have potential roles as a biomarker and/or a therapeutic target in colorectal cancer." (PMID 26856330, 2016). "In a mouse colorectal cancer model, lncRNA LINC00941 and lncRNA Tug1 promote the migratory and invasive ability of colorectal cancer, thereby expediting lung metastasis." (PMID 38818471, 2024). "By analyzing the expression of 17 lncRNAs and 31 circRNAs in biopsies and serum exosomes from colorectal cancer (CRC) patients through qRT-PCR, we detected CCAT1, CCAT2, HOTAIR, and UCA1 upregulation and CDR1AS, MALAT1, and TUG1 downregulation in biopsies." (PMID 30195762, 2018). "However, the role of TUG1 in colorectal cancer remains unclear." (PMID 26856330, 2016). "For instance, lincRNA DQ786243 contributed to proliferation and metastasis of colorectal cancer both in vitro and in vivo; GHET1 and TUG1 promoted colon cancer progression; GAS5 contributed to lymphatic metastasis in colorectal cancer; Linc00152 and LincRNA-ROR hold prognostic value." (PMID 31497531, 2019). "TUG1 has also been shown to enhance tumor angiogenesis and VEGF expression through inhibition of miR-299 in glioblastoma cells, and to promote colorectal cancer cell proliferation and migration by induction of the epithelial-mesenchymal transition (EMT) process." (PMID 29371936, 2017). "Increased lncRNA TUG1 expression promotes cell proliferation, metastasis and inhibits cell apoptosis to act as an oncogene in various cancers, such as breast cancer (BRC), colorectal cancer (CRC), ovarian cancer (OC) and small cell lung cancer (SCLC)." (PMID 29029461, 2017).